THRAP3 (thyroid hormone receptor associated protein 3)
Description:
Involved in pre-mRNA splicing. Remains associated with spliced mRNA after splicing which probably involves interactions with the exon junction complex (EJC). Can trigger mRNA decay which seems to be independent of nonsense-mediated decay involving premature stop codons (PTC) recognition. May be involved in nuclear mRNA decay. Involved in regulation of signal-induced alternative splicing. During splicing of PTPRC/CD45 is proposed to sequester phosphorylated SFPQ from PTPRC/CD45 pre-mRNA in resting T-cells. Involved in cyclin-D1/CCND1 mRNA stability probably by acting as component of the SNARP complex which associates with both the 3'end of the CCND1 gene and its mRNA. Involved in response to DNA damage. Is excluced from DNA damage sites in a manner that parallels transcription inhibition; the function may involve the SNARP complex. Initially thought to play a role in transcriptional coactivation through its association with the TRAP complex; however, it is not regarded as a stable Mediator complex subunit. Cooperatively with HELZ2, enhances the transcriptional activation mediated by PPARG, maybe through the stabilization of the PPARG binding to DNA in presence of ligand. May play a role in the terminal stage of adipocyte differentiation. Plays a role in the positive regulation of the circadian clock. Acts as a coactivator of the CLOCK-BMAL1 heterodimer and promotes its transcriptional activator activity and binding to circadian target genes.
Synonyms: Trap150; BCLAF2
Tractability: PROTAC: UniProt records ubiquitination sites on it; ubiquitination databases record sites on it; its protein half-life has been measured; a small molecule that binds it is known.
Gene: Protein-coding gene on chromosome 1 (36,224,392 to 36,305,376, forward strand). Ensembl gene ENSG00000054118.
Subcellular location: Nucleus; Nucleus, nucleoplasm; Nucleus speckle
Subcellular location (Human Protein Atlas): Nuclear speckles
Pathways (Reactome):
Developmental Biology: Transcriptional regulation of white adipocyte differentiation
Metabolism: PPARA activates gene expression
Gene Ontology:
Molecular function: nuclear thyroid hormone receptor binding; phosphoprotein binding; protein binding; RNA binding; transcription coactivator activity; transcription coregulator activity; DNA binding; nuclear vitamin D receptor binding; RNA polymerase II cis-regulatory region sequence-specific DNA binding
Biological process: mRNA stabilization; nuclear-transcribed mRNA catabolic process; positive regulation of circadian rhythm; positive regulation of DNA-templated transcription; positive regulation of mRNA splicing, via spliceosome; positive regulation of transcription by RNA polymerase II; regulation of alternative mRNA splicing, via spliceosome; circadian rhythm
Cellular component: exon-exon junction complex; extracellular exosome; mediator complex; nuclear speck; nucleoplasm; nucleus
Genetic constraint (gnomAD): Loss-of-function variants: 16 observed, 99.44 expected, observed/expected ratio (o/e) 0.16, 90% interval 0.11 to 0.24. The upper end of that interval is the gene's LOEUF score, 0.24, which puts it in group 1 of 6, group 1 being the genes least tolerant of losing a copy. Missense variants: 986 observed, 1,243 expected, observed/expected ratio (o/e) 0.79, 90% interval 0.75 to 0.84. Synonymous variants: 406 observed, 441.7 expected, observed/expected ratio (o/e) 0.92, 90% interval 0.85 to 1.
Homologues: Orthologues: chimpanzee THRAP3 (100% identical), macaque THRAP3 (99% identical), pig THRAP3 (97% identical), dog THRAP3 (97% identical), rabbit THRAP3 (96% identical), guinea pig THRAP3 (95% identical), rat Thrap3 (94% identical), mouse Thrap3 (93% identical), tropical clawed frog thrap3 (65% identical), zebrafish thrap3b (40% identical), zebrafish thrap3a (38% identical). Paralogues in human: BCLAF1 (38% identical), BCLAF3 (16% identical).
Diseases named in the same sentence as THRAP3 in open-access papers:
THRAP3 is named in the same sentence as 45 diseases in open-access papers, as found by Europe PMC text mining. Sharing a sentence is not in itself a finding about the gene and the disease. The quoted sentences say what the papers report.
breast carcinoma (3 papers, 2021 to 2022). "SRSF1 interacts with Thrap3 (thyroid hormone receptor associated protein 3) and DDX5, which promote R-loop resolution in breast cancer cells." (PMID 35954483, 2022). "In the breast cancer cell group THRAP3, RHOA, and QRICH1 were the top three stably expressed genes, while B2M, TUBA1A, and ACTB were the least stably expressed genes." (PMID 34895237, 2021). "Surprisingly, THRAP3 was the most stably expressed gene according to all five algorithms in breast cancer cell lines." (PMID 34895237, 2021). "In the case of studies including both breast cancer tissue and cell line research, the THRAP3 + RHOA + QRICH1 combination would be optimal." (PMID 34895237, 2021). "In the breast cancer cell line group, THRAP3, RHOA, and QRICH1 were the three most stably expressed genes, while B2M, ACTB, and TUBA1A were the least stably expressed genes." (PMID 34895237, 2021). "The growth of Thrap3 knockdown MCF7 breast cancer cell lines was significantly inhibited, and RNaseH1 expression restored the cell proliferation capacity." (PMID 34697388, 2021). "Our results show that RG combinations SF1 + TRA2B + THRAP3 and THRAP3 + RHOA + QRICH1 showed stable expression in breast cancer tissues and cell lines, respectively, and that they displayed good interchangeability." (PMID 34895237, 2021). "Our results indicated that SF1, TRA2B, and THRAP3 were the top 3 stably expressed RGs in breast cancer tissues and that THRAP3, RHOA, and QRICH1 were the top 3 stably expressed RGs in breast cancer cell lines." (PMID 34895237, 2021). "For all breast cancer tissue and cell line samples, THRAP3, RHOA, QRICH1 were the most stably expressed genes, and TUBA1A, B2M, ACTB were the least stably expressed RGs." (PMID 34895237, 2021). "In the breast cancer cell group, THRAP3, DNAJC8, and RPL13A were the three most stably expressed genes, while TUBA1A, B2M, and ACTB were the least stably expressed genes." (PMID 34895237, 2021). "In the breast cancer cell lines, THRAP3, RHOA, and QRICH1 were the most stably expressed RGs." (PMID 34895237, 2021). "Therefore, we considered the multi-RG combination SF1 + TRA2B + THRAP3 + RHOA + QRICH1 as the most promising choice for breast cancer research (both in breast cancer tissues and cell lines)." (PMID 34895237, 2021). "In the breast cancer tissue group, the three most stably expressed genes (with the lowest M values) were SF1, THRAP3, and TARDBP, while GAPDH, DNAJC8, and B2M were the least stably expressed genes." (PMID 34895237, 2021). "The top three genes for breast cancer tissues and cell lines were SF1 + TRA2B + THRAP3 and THRAP3 + RHOA + QRICH1, respectively, and therefore a total of 5 RGs (SF1, TRA2B, THRAP3, RHOA, QRICH1) should be considered." (PMID 34895237, 2021). "According to the ΔCt method, TRA2B, RHOA, and THRAP3 were the most stably expressed genes, while DNAJC8, GAPDH, and B2M were the least stable genes in the breast cancer tissue group, which was consistent with the analysis according to NormFinder." (PMID 34895237, 2021). "There was also a moderate-to-high correlation (R2 from 0.621 to 0.709 in breast cancer tissues, and R2 from 0.600 to 0.916 in breast cancer cell lines) between unstable RGs and SF1 + TRA2B + THRAP3 + RHOA + QRICH1." (PMID 34895237, 2021). "There was a high correlation (R2 from 0.815 to 0.979 in breast cancer tissues, and R2 from 0.927 to 0.995 in breast cancer cell lines) between stable RGs and SF1 + TRA2B + THRAP3 + RHOA + QRICH1." (PMID 34895237, 2021). "In the breast cancer tissue group, TRA2B, RHOA, and THRAP3 were the most stable genes, and DNAJC8, GAPDH, and B2M were the most unstable genes." (PMID 34895237, 2021). "In breast cancer cell lines, when the optimal RG combinations SF1 + TRA2B + THRAP3 + RHOA + QRICH1, SF1 + TRA2B + THRAP3, or THRAP3 + RHOA + QRICH1 were used for normalization, the expression of FAAH was highest in MCF-7 cells, followed by MCF-10A cells, and was least in MDA-MB-231 cells." (PMID 34895237, 2021).
breast carcinoma (continued). "Therefore, we recommend that SF1 + TRA2B + THRAP3 and THRAP3 + RHOA + QRICH1 be adopted as the RG combinations for breast cancer tissue and cell line research, respectively." (PMID 34895237, 2021). "In addition, THRAP3, TARDBP, and YY1 were the most stably expressed genes in the breast cancer cell lines, while B2M, TUBA1A, and ACTB were the least stably expressed genes." (PMID 34895237, 2021). "Therefore, to confirm the roles of these genes on the vital regulatory mechanisms in breast cancer, we compared the potential role of novel RGs (SF1, TRA2B, THRAP3, RHOA, and QRICH1) vs. traditional RGs (ACTB, and GAPDH) in the normalization of target gene expression." (PMID 34895237, 2021).
diabetes (3 papers, 2015 to 2021). "It was suggested that interfering with docking of THRAP3 on PPARγ could be a strategy to screen for compounds for diabetes treatment." (PMID 34526909, 2021). "An evidence demonstrating a role for ESRRA (estrogen related receptor alpha) and THRAP3 in diabetes, but these genes might be liable for development of HF." (PMID 34218797, 2021).
bladder cancer (1 paper, 2024). "Moreover, LINC00162, transcribed from the SE region in bladder cancer, interacts with THRAP3, thereby disrupting THRAP3’s ability to positively regulate PTTG1IP expression." (PMID 38542080, 2024).
breast adenocarcinoma (1 paper, 2021). "As observed in U2OS cells, Thrap3 depletion reduced EdU-incorporation in MCF7 breast adenocarcinoma cells, indicating decreased DNA replication." (PMID 34697388, 2021).
breast tumor (1 paper, 2021). "In the breast tumor tissue group, the 3 most stably expressed RGs were SF1, TRA2B, and THRAP3." (PMID 34895237, 2021).
colon cancer (1 paper, 2023). "Because the S248 and S253 residues of THRAP3 are very close in the sequence, the function of THRAP3S253p in colon cancer was also investigated for comparison." (PMID 37031867, 2023).
colorectal cancer (1 paper, 2024). A primary or metastatic malignant neoplasm that affects the colon or rectum. "In BRAF-mutated colorectal cancer, nuclear PD-L1 accelerated tumor progression by interacting with THRAP3." (PMID 38333620, 2024). "THRAP3 was reported to be a tumor suppressor in BRAF-mutated colorectal cancer." (PMID 38333620, 2024).
depression (1 paper, 2026). "Two genes, ADAMTS7 and THRAP3, warrant further investigation as potential targets for therapeutic interventions to manage MASLD and depression among Mexican Americans." (PMID 41898876, 2026). "Based on the Fisher Combined Test, only THRAP3 (p = 3.0 × 10-2) and ADAMTS7 (p = 2 × 10-2) were jointly significant for depression (BDI-II) and AST, ALT, AST/ALT ratio, FAST, and CAP (kPa)." (PMID 41898876, 2026).
endometrial cancer (1 paper, 2024). Primary or metastatic malignant neoplasm involving the endometrium (mucous membrane that lines the endometrial cavity). "The mutation frequency of the THRAP3 gene in endometrial cancer, ovarian epithelial cancer, and melanoma exceeds 5%." (PMID 38333620, 2024). "Three tumors with the highest alteration frequency of THRAP3 were endometrial cancer, ovarian epithelial cancer, and melanoma, respectively." (PMID 38333620, 2024).
esophageal squamous cell carcinoma (1 paper, 2024). Esophageal squamous cell carcinoma (ESCC) is a type of esophageal carcinoma (EC) that can affect any part of the esophagus, but is usually located in the upper or middle third. "We performed GSEA and GSVA to investigate the biological characteristics of THRAP3 expression in six cancers, including esophageal squamous cell carcinoma (ESCA), LGG, LIHC, LUSC, PAAD, and SKCM." (PMID 38333620, 2024).
Hepatic steatosis (1 paper, 2023). Steatosis is a term used to denote lipid accumulation within hepatocytes. "To evaluate the functional role of Thrap3 in NAFLD, we examined Thrap3 expression in various hepatic steatosis-mimicking conditions, including cell lines and mouse models." (PMID 37524868, 2023). "However, in the NAFLD mimic HFD model, Thrap3 LKO mice exhibited attenuated HFD-induced hepatic steatosis." (PMID 37524868, 2023).
hepatocellular carcinoma (1 paper, 2023). A malignant tumor that arises from hepatocytes. "In addition, we observed that Thrap3 expression was positively correlated with histological fatty changes in normal sections from livers of hepatocellular carcinoma patients." (PMID 37524868, 2023).
hyperparathyroidism (1 paper, 2023). Hyperfunction of the parathyroid glands resulting in the overproduction of parathyroid hormone. "The cohort was screened for gene variants of ADCK1, CCD1, FAT3, and THRAP3 that have previously been associated with PC as described in the literature but that were not included in the BpG hyperparathyroidism gene panel assessment." (PMID 36900197, 2023).
Insulin resistance (1 paper, 2021). Increased resistance towards insulin, that is, diminished effectiveness of insulin in reducing blood glucose levels. "The authors found that knockdown of Thrap3 led to restored glucose tolerance in high-fat diet fed mice, supporting their model of Thrap3’s role in insulin resistance." (PMID 34339734, 2021).
lung adenocarcinoma (1 paper, 2024). A carcinoma that arises from the lung and is characterized by the presence of malignant glandular epithelial cells. "Single-cell sequencing (ScRNA-seq) analysis was employed to investigate the proportions of each cell type in lung adenocarcinoma (LUAD) and adjacent normal tissues, along with the expression levels of THRAP3 within each cell type." (PMID 38333620, 2024).
lung carcinoma (1 paper, 2024). "We aimed to conduct a comprehensive analysis of THRAP3 and validate its expression levels in lung cancer." (PMID 38333620, 2024). "The protein levels of THRAP3 were explored in lung cancer by immunohistochemistry (IHC) analysis." (PMID 38333620, 2024).
Obesity (1 paper, 2023). Accumulation of substantial excess body fat. "Jang Hyun Choi of the Ulsan National Institute of Science and Technology, South Korea, and colleagues previously demonstrated that a protein called Thrap3 contributes to obesity-related insulin resistance." (PMID 37524868, 2023). "Taken together, these results demonstrate that liver-specific deletion of Thrap3 confers systemic protection against diet-induced obesity and NAFLD without affecting the expression of FA β-oxidation- and lipogenesis-associated genes." (PMID 37524868, 2023).
renal carcinoma (1 paper, 2022). A carcinoma arising from the epithelium of the renal parenchyma or the renal pelvis. "Immunohistochemical staining results of the bioinformatics analysis showed that the protein levels of GNA11 and THRAP3 were significantly decreased in renal cancer tissues, and the protein levels of CSNK1E did not change significantly." (PMID 35877357, 2022).
skin cutaneous melanoma (1 paper, 2024). "THRAP3 elevation had a poor prognosis in kidney renal clear cell carcinoma and a prolonged survival time in kidney chromophobe, brain lower-grade glioma and skin cutaneous melanoma, as indicated by the KM curve." (PMID 38333620, 2024).
steatosis (1 paper, 2023). Increased lipid within the cytoplasm of cells. "Human HepG2 cells were stimulated with free fatty acids (FFAs) to establish in vitro hepatocyte steatosis models, and Thrap3 expression was measured." (PMID 37524868, 2023).
type 2 diabetes (1 paper, 2025). "Along this line, a thyroid hormone receptor-associated protein (Thrap3, p = 0.00015), linked to T cell activity and type 2 diabetes, is one of the top upregulated genes in males." (PMID 41034487, 2025).
uveal melanoma (1 paper, 2024). A melanoma derived from melanocytes of the uveal tract. "In KIRC and uveal melanoma (UVM), THRAP3 expression in patients aged ≤ 65 years is higher than that in patients aged >65 years." (PMID 38333620, 2024).
cancer (13 papers, 2014 to 2025). A tumor composed of atypical neoplastic, often pleomorphic cells that invade other tissues. "This study focused on the function of Thrap3 in R-loop-associated DNA damage in cancer cells and identified Thrap3 as a novel regulator of R-loop-associated DNA damage." (PMID 34697388, 2021). "To examine this we tested the impact of two cancer-associated mutations R101* and R837* on THRAP3 function." (PMID 29112714, 2017). "Gene mutation analysis showed that THRAP3 gene mutations are prevalent in most cancer types." (PMID 38333620, 2024). "Several studies have implicated THRAP3 in the development of certain cancers." (PMID 38333620, 2024). "Loss of THRAP3 results in sensitivity to DNA damaging agents, genomic instability, and defective DNA repair, which are in themselves promising targets for chemotherapy of cancers." (PMID 34526909, 2021). "Finally, we show that cancer-associated mutations identified within THRAP3 induce a severe defect in DNA double strand break (DSB) repair capability." (PMID 29112714, 2017). "Moreover, we show that cancer associated mutations within THRAP3 result in deregulated processing of THRAP3/BCLAF1-regulated transcripts and consequently defective DNA repair." (PMID 29112714, 2017). "HBV integration at the THRAP3 locus was also reported, as well as mutations in other cancers." (PMID 25526364, 2014). "Thrap3 is recruited to R-loop-forming loci, and loss of Thrap3 increases R-loop accumulation and DNA damage, thereby increasing the amount of replication stress, demonstrating that Thrap3 plays an important role in resolving R-loop-associated DNA damage in cancer cells." (PMID 34697388, 2021). "The top cancer genes with recurrent variants included: STAT2 (33%), DMNT1 (27%), HSP90AA1 (17%), CDK4, NOTCH2, THRAP3, and SALL4 (13% each)." (PMID 41353477, 2025). "THRAP3 is highly expressed in 12 tumors and lowly expressed in 7 tumors, according to differential analysis in 33 types of cancer." (PMID 38333620, 2024). "Pan-cancer analysis data revealed that THRAP3 is significantly correlated with prognosis, and TME in multiple malignancies." (PMID 38333620, 2024). "Thrap3 has been reported as an RNA-binding protein or transcription cofactor that regulates alternative splicing of pre-mRNAs, cancer cell growth, differentiation and DNA damage." (PMID 37524868, 2023). "When the team suppressed Thrap3 expression, they saw an increase in R-loops in both normal and cancer cells." (PMID 34697388, 2021). "Importantly, THRAP3 deficiency has been observed in multiple cancer types, such as breast and ovarian cancers, oral squamous cell carcinomas, liver tumors and parathyroid carcinomas, suggesting that it may function as a tumor suppressor gene, possibly through a role in the DDR." (PMID 29112714, 2017). "Moreover, as cancer associated mutations within THRAP3 result in deregulated export of target transcripts and a subsequent DNA repair defect, this data suggests that THRAP3/BCLAF1 may function to suppress tumor development and/or act as biomarkers of response to therapy." (PMID 29112714, 2017). "In cancer cells, THRAP3 facilitates cell growth by inducing R-loop resolution." (PMID 38333620, 2024). "Our results reveal differential expression of THRAP3 in multiple cancers relative to matched-normal tissues, and THRAP3 could be a prognostic biomarker in specific cancer types." (PMID 38333620, 2024). "Thus, THRAP3 serves as a potential biomarker and immunotherapy target in various cancers, which is worth further study." (PMID 38333620, 2024).